LEP (leptin)
Diseases named in the same sentence as LEP in open-access papers (continued):
Sharing a sentence is not in itself a finding about the gene and the disease.
Obesity (continued). "Although common forms of human obesity are not due to such defects in leptin or its receptor, obese subjects have generally been found to be leptin-resistant." (PMID 19007436, 2008). "The obese mice also develop hyperglycaemia and type 2 diabetes, which occurs as a consequence of obesity rather than a primary effect of leptin." (PMID 18489748, 2008). "The significant correlation of leptin to selected anthropometric measurements of obesity is confirmed in non-diabetic Saudi Subjects." (PMID 17617917, 2007). "The fact, that obese individuals did not adequately respond to increased leptin levels with reduced food intake implicates that obesity is also influenced by leptin resistance." (PMID 17445271, 2007). "Serum levels of the peptide hormone leptin are increased in obesity in proportion to body fact mass, recent data suggest that leptin receptors are expressed by BO and OAC and studies have also shown that leptin can stimulate proliferation of OAC cells in culture." (PMID 17559672, 2007). "Leptin and NPY levels showed inverse values in two different obesity types." (PMID 17721641, 2007). "Although leptin has not become the panacea for obesity that was once hoped, it has undoubted actual and potential clinical utility." (PMID 17448988, 2007). "The higher leptin level among diabetics and pre-diabetics is not related to differences in anthropometric measures of obesity." (PMID 17617917, 2007). "The leptin gene was isolated by Friedman's group, through positional cloning from ob/ob mice that failed to produce leptin and displayed extreme obesity and hyperphagia." (PMID 16300680, 2005). "Another form of mouse obesity, designated db/db, demonstrates symptoms similar to those observed in ob/ob mice, but the db/db mice failed to be rescued by leptin administration." (PMID 16300680, 2005). "Compared to VAT, SCAT is the predominant source of leptin, yet patients with VAT obesity may tend to have higher leptin levels than normal, lean individuals but lower than those with predominantly SCAT or subcutaneous obesity." (PMID 15530168, 2004). "As leptin hyperpolarizes a sub-population of hypothalamic neurones by opening KATP channels, it is feasible that at least part of the anti-obesity action of BVT.12777 may be through the activation of this potassium channel." (PMID 15329154, 2004). "This suggests that the hyperleptinemia of predominantly VAT obesity is not high enough to overcome a leptin resistance due to the accumulation of ectopic fat in nonadipose tissues, which leads to lipotoxicity and ultimately the metabolic syndrome." (PMID 15530168, 2004). "Therefore, leptin levels alone are unlikely to explain why obesity accelerates puberty in girls more than in boys." (PMID 41240372, 2026). "Together, these findings indicate that impaired central leptin signalling induces co-ordinated endocrine and metabolic disturbances in the absence of obesity, supporting a role for altered central neuroendocrine regulation in the early development of metabolic dysfunction." (PMID 42097975, 2026). "However, upon adjusting for obesity, CXCL5 and LEP were attenuated indicating that their expressions may be mediated by obesity." (PMID 41507467, 2026). "However, the obverse, that overfeeding-induced increased leptin levels prevent obesity development, has not been experimentally determined." (PMID 40702736, 2025). "The specific upregulation of LEP in OBS and CREM2 in NW cultures further highlights the complex and context-dependent nature of folic acid’s influence on gene expression, indicating potential therapeutic pathways for tailored folic acid interventions in SLE, particularly in individuals with obesity." (PMID 40292473, 2025). "Additionally, the A allele of the rs7739039 variant is associated with reduced leptin levels in general/control subjects (SMD = -0.25 ng/mL, 95% CI = -0.46 to -0.03 ng/mL, p = 0.03), but not in overweight/obesity patients." (PMID 41158627, 2025).
Obesity (continued). "However, treatment with Ang 1-7 decreases visceral adipose tissue mass and adipose leptin, suggesting that the ACE2/Ang 1-7 pathway could be a potential therapeutic target for obesity and T2DM." (PMID 40564980, 2025). "This review synthesizes evidence linking GDF15 to obesity, diabetes, cardiovascular diseases, metabolic liver disorders, cachexia, sarcopenia, and aging while exploring its interactions with key metabolic factors including FGF21, GLP-1, leptin, and glucocorticoids." (PMID 40837873, 2025). "Additionally, we did not measure obesity-related markers such as insulin, C-peptide, glucagon, leptin, or cortisol." (PMID 41323348, 2025). "Importantly, biomarkers such as CRP, IL-6, TNF-α, and leptin are frequently elevated in individuals with overweight or obesity independent of dietary exposures." (PMID 41010537, 2025). "The present study showed that children with comorbid asthma and obesity/overweight had higher IL-6, TNF-α, and leptin, and lower 25-(OH) D3, IL-10, and IL-13 than children with asthma alone, and had lower IL-10 and higher IL-6, IL-13, and leptin than children with obesity/overweight alone." (PMID 40083433, 2025). "Obesity has a similar effect, but the decrease in leptin and APLNR expression was not significant." (PMID 41302116, 2025). "However, in individuals with obesity, leptin levels are often elevated without corresponding physiological effects—an indication of leptin resistance." (PMID 41226331, 2025). "Additionally, although the GLM analysis adjusted for sex, age, and family history of obesity (which were not evenly distributed between groups), some inconsistencies remained in the outcomes of leptin and adiponectin levels and body composition indices." (PMID 40661686, 2025). "Notably, obesity has been shown to exacerbate the experimental autoimmune encephalomyelitis (EAE) mouse model of MS, leading to BBB disruption, with leptin potentially contributing to this effect." (PMID 40019662, 2025). "Because our cohort did not include individuals with overt obesity or biochemical evidence of leptin resistance, these complex mechanisms could not be directly assessed." (PMID 40521397, 2025). "Furthermore, increased leptin action on Lepr neurons in the dorsomedial hypothalamic nucleus (DMH) may contribute to elevated SNS outflow and blood pressure in obesity." (PMID 40393800, 2025). "Therefore, the elevated levels of FT3 and TSH in patients with OSAHS and obesity, as well as the correlation of TSH with BMI and L-SaO2, may primarily be attributed to the combined effects of leptin and inflammation resulting from oxidative stress." (PMID 40438137, 2025). "However, in individuals with obesity, leptin levels are often elevated, yet this does not induce satiety due to peripheral or central leptin resistance." (PMID 41439942, 2025). "For instance, obesity-related factors such as elevated levels of pro-inflammatory cytokines (e.g., IL-6, TNF-α) and adipokines (e.g., leptin) may promote an immune-stimulatory environment that facilitates a stronger anti-tumor response when ICIs are administered." (PMID 40040878, 2025). "In addition, CRP regulates the expression of key adipokines and inflammatory mediators, including adiponectin, TNF-α, leptin, IL-6, and PPAR-γ, which may underpin its involvement in insulin resistance, obesity, and metabolic syndrome." (PMID 40001459, 2025). "Adipokines, such as leptin and adiponectin, chemokines, such as CCL7, and metabolites, such as glucose and FFAs, were the targets selected to be quantified as they are key players in prostate tumorigenesis and are differentially secreted by adipocytes in obesity." (PMID 41440554, 2025). "As the name suggests, leptin resistance is manifested as an abnormal increase in leptin levels in the blood, but the body is not sensitive to leptin, which prevents it from exerting its corresponding beneficial functions and ultimately leads to obesity." (PMID 39812542, 2025).
Obesity (continued). "Importantly, enlarged adipocytes were associated with lower subcutaneous and visceral adiponectin, omentin, and visfatin mRNA expression in individuals with obesity, and with higher visceral LEP mRNA expression in individuals without obesity." (PMID 41271970, 2025). "However, in obesity, leptin resistance often develops, characterized by elevated circulating levels of leptin without corresponding satiety signals." (PMID 40710568, 2025). "In total, our results reveal ArcGABA non-LepR neurons as an alternative neural basis for leptin resistance and effective therapeutic target against obesity and suggest that improving cellular leptin resistance alone may not be able to reduce DIO." (PMID 40540394, 2025). "Human studies indicate that women with obesity have lower clinical and ongoing pregnancy rates following IVF, and in vitro evidence points to a mechanism involving the inhibition of granulosa cell proliferation and the promotion of apoptosis by high levels of leptin." (PMID 40755647, 2025). "While modifying lifestyle, such as reducing caloric intake, increasing dietary fiber and nutrients, and increasing physical exercise, contributes to body weight management, these behavioral measures are not sufficient to treat obesity or improve leptin resistance." (PMID 41016636, 2025). "We found that betaine intervention significantly reduced serum leptin levels and body weight gain in HFD-fed rats when HFD was continuously administered, suggesting that the anti-obesity effect of betaine may be related to leptin signaling and carbohydrate metabolism." (PMID 40709342, 2025). "Obesity also creates a state of chronic low-grade inflammation-excess adipose tissue secretes pro-inflammatory cytokines (e.g., IL-6, TNF-α) and alters adipokine profiles (leptin up, adiponectin down), fostering a microenvironment conducive to neoplastic growth." (PMID 41041441, 2025). "Both Y1 and Y5 receptor antagonists are being explored as a potential therapeutic strategy for obesity and related metabolic disorders by influencing satiety and energy balance, while the direct link between Y1/Y5 receptor antagonisms and leptin resistance is not fully elucidated." (PMID 41016636, 2025). "Notably, caloric restriction-induced weight loss did not restore the leptin effect and may only serve to enhance the amylin effect, with the diminished response perhaps reflecting chronic leptin receptor desensitization or altered hypothalamic signaling pathways after a state of extreme obesity." (PMID 40192745, 2025). "In obesity, elevated leptin levels are not protective, consistent with central leptin resistance." (PMID 41516046, 2025). "It has been described that rodent models lacking leptin action as a consequence of aleptinemia develop hyperphagia and obesity resulting in ectopic fat accumulation and steatosis in non-adipose tissues such as liver, heart, pancreatic islets, kidneys, and skeletal muscle." (PMID 40415699, 2025). "The higher leptin concentrations in non-obese healthy subjects might be the result of nutritional programming through maternal undernutrition or obesity and even periconceptional maternal obesity." (PMID 40152811, 2025). "However, leptin stimulates the reduction in food intake and metabolic expenditure, so it should not be increased in a condition such as obesity." (PMID 40002337, 2025). "In conditions such as obesity, aging, insulin resistance, dyslipidemia, or chronic oxidative stress, PVAT undergoes phenotypic switching, adopting a pro-inflammatory profile leading to increased secretion of leptin, IL-6, and TNF-α, while decreasing adiponectin levels." (PMID 40943241, 2025). "In conclusion, our findings suggest that leptin, through its effects on H3K27 epigenetic changes, plays a pivotal role in regulating CCL2/MCP‐1 expression in ASCs, revealing a novel mechanism by which leptin may contribute to WAT inflammation and the pathophysiology of obesity." (PMID 40518865, 2025).
Obesity (continued). "However, in the long term, leptin induces the expression of suppressor of cytokine signaling 3 (SOCS3), a negative feedback inhibitor that blocks STAT3 activation and contributes to leptin and insulin resistance in the context of obesity." (PMID 40872612, 2025). "Furthermore, analysis of human data provided evidence for a negative feedback loop between TET2 and leptin in the context of obesity." (PMID 40620794, 2025). "Several experimental studies have shown that, despite obesity, models in which the expression of leptin or leptin receptors was inhibited did not exhibit an increased risk of mammary cancer, suggesting that leptin signaling plays a crucial role in tumorigenesis rather than weight gain itself." (PMID 38255203, 2024). "In a cohort of 5- to 9-year-old prepubertal children with overweight and obesity, we observed early insulin resistance driven by high insulin levels, as fasting glucose levels remained normal, and elevated markers of inflammation including CRP and the leptin/adiponectin ratio." (PMID 38680993, 2024). "Adipocyte-specific deletion of BDNF/TrkB results in resistance to HFD-induced obesity, particularly in females,indicating that adipocytic BDNF is essential for the adipocytic response to central BDNF signaling and the production of adipocytokines, including leptin." (PMID 39655343, 2024). "Studies with other characteristics could better consolidate the effect of higher leptin concentrations in women with more pronounced disease activity, without considering their role in obesity." (PMID 38792501, 2024). "Likewise, LGG has been shown to be able to restore the response to exogenous leptin in an in vivo model of HFD-induced leptin resistance, suggesting that LGG supplementation may reduce leptin resistance, commonly observed in obesity." (PMID 39593945, 2024). "Notably, in female mice, adipocyte-derived leptin is a positive regulator of aldosterone synthesis in the zona glomerulosa of the adrenal glands independent of obesity." (PMID 39493777, 2024). "In addition to leptin, multiple factors might be involved in paraventricular nucleus signalling to mediate SNS activation and BP increase in obesity." (PMID 38186879, 2024). "In contrast, from a novel perspective, we found that higher leptin concentrations—a characteristic of being female and not of obesity—could influence pain perception among women." (PMID 38792501, 2024). "Our main objective was to evaluate the levels of adiponectin, leptin, TNFα, IL6, and IGFs 1 and 2 in endometrial cancer patients compared to control patients with benign gynaecological conditions and to assess their relationship with obesity using the WHO BMI classification." (PMID 38339282, 2024). "Consistently, in the leptin-deficient (ob/ob) obese mice, adipocyte expression of TET2 were elevated when compared with lean controls, suggesting that leptin, rather than obesity, negatively regulated the expression of TET2 in adipocytes." (PMID 38561362, 2024). "Anti-obesity compounds can influence differentiation, synthesis and lipolysis by modulating signaling pathways such as inflammation signaling pathways (NF-κb, MAPK, AP-1, etc.), glycometabolism signaling pathways (PGC-1α, ChREBP, GLUT1, etc.), adipocytokines (leptin, adiponectin), and so on." (PMID 38674793, 2024). "In contrast with obesity, the pro-inflammatory cytokine-producing T helper type 1 (TH1) cells, CD8+ cytotoxic T cells, and NK cells that produce IFNγ become abundant in the adipose tissue due to excess leptin, which leads to M1 macrophage accumulation and polarization." (PMID 39040042, 2024). "In obesity, leptin is not able to adequately regulate energy expenditure." (PMID 39770044, 2024). "Therefore, it appears that the reduced sensitivity to leptin, rather than leptin concentration, contributes to the delayed decline of adipocyte Tet2 levels in eWAT during obesity." (PMID 38561362, 2024).
Obesity (continued). "However, in multifactorial obesity, exogenous leptin administration does not improve insulin sensitivity, possibly due to leptin resistance." (PMID 38289144, 2024). "Genes in the leptin–melanocortin pathway, such as leptin (LEP), leptin receptor (LEPR), melanocortin-4 receptor (MC4R), adenylyl cyclase 3 (ADCY3), and brain-derived neurotrophic factor (BDNF) genes, are established contributors to obesity and insulin resistance." (PMID 38674857, 2024). "Tg, Tc, leptin, and TNF-α were positively correlated with denovo624899 abundance, indicating that denovo624899 in E. miletus may have a preference for high-fat foods, potentially contributing to obesity under conditions of high-fat food consumption." (PMID 39050639, 2024). "Importantly, due to the involvement of PHIP in the leptin-melanocortin pathway, affected individuals with CHUJANS who suffer from therapy resistant obesity can participate in a clinical trial with an anti-obesity drug (setmelanotide (MC4R-agonist), ClinicalTrials.gov identifier: NCT04963231)." (PMID 38787418, 2024). "In some situations, such as obesity, a highly emerging issue in paediatrics, a non-dynamic assessment of the rise of gonadotropin appears more appropriate than a GnRH test given the effect of leptin on kisspeptin neurons." (PMID 38514451, 2024). "In addition to leptin and ghrelin, other physiological factors may influence the impact of SJL in obesity, such as insulin sensitivity, cortisol secretion, intestinal peptides, and alterations in the autonomous nervous system." (PMID 39203711, 2024). "Human SCs express obesity-related genes (ORG, MC4R, GNPDA2, TMEM18, and FTO), and the expression of GNPDA2 and TMEM18 proteins in SCs has been reported to increase after incubation with leptin and ghrelin, leading to a modulation of the nutritional support provided for spermatogenesis." (PMID 38961093, 2024). "Additionally, Leptin (LEP) displayed a biphasic fluctuation in GCF concentration during OTM, potentially influenced by a range of factors including the applied force, duration of treatment, and individual variables such as obesity." (PMID 39307846, 2024). "Previous research indicates that acute exercise alone (< 12 weeks) is not effective for reducing leptin levels in obesity, with greater benefits following moderate- and high-intensity aerobic exercise as well as resistance training performed for > 12 weeks (3–4 times a week)." (PMID 38933888, 2024). "This relationship may reflect the “obesity paradox”, where higher leptin levels in non-cachectic patients are indicative of better nutritional status and prognosis." (PMID 39682585, 2024). "This may be due to the fact that obesity exerts systemic effects on various tissues, leading to increased levels of non-esterified fatty acids (NEFAs), insulin, leptin, and inflammatory factors, as well as decreased adiponectin levels." (PMID 38431748, 2024). "Patients with obesity and asthma have higher leptin levels than non-obese populations." (PMID 39065704, 2024). "Importantly, although human obesity is associated with PYY deficiency, PYY3-36 retains its anorexigenic effects in this group, without the development of resistance like that seen with leptin." (PMID 38019584, 2024). "Moreover, perirenal/sinus fat produces adipocytokines such as leptin, resistin, IL-1β, IL-6, TNF-α, etc., which may also contribute to obesity-related hypertension by stimulating inflammatory processes and by activating the SNS and the RAAS." (PMID 38186879, 2024). "Thus, ovarian canonical and noncanonical leptin signalling control the activity of the NLRP3 inflammasome in the course of obesity in mice." (PMID 38580672, 2024). "Apparently, sex, patient nutritional status, leptin resistance, or age all influence this, so it is not clear whether obesity-induced cardiac hypertrophy is the result of leptin or resistance to its cardioprotective effects." (PMID 38397015, 2024).